CCL5 (C-C motif chemokine ligand 5)
Diseases named in the same sentence as CCL5 in open-access papers (continued):
Sharing a sentence is not in itself a finding about the gene and the disease.
malaria (34 papers, 2005 to 2025). Malaria is a serious and sometimes fatal disease caused by a parasite that commonly infects a certain type of mosquito which feeds on humans. "Moreover, reduced CCL5 production was associated with the suppression of erythropoiesis and malaria-induced thrombocytopaenia, suggesting that CCL5 may be involved in the regulation of the erythorpoietic response during malaria infection." (PMID 24476686, 2014). "It has already been reported that children with CM having lowered levels of CCL5 (RANTES) were more likely to die from this complication of severe malaria than children with higher levels of RANTES." (PMID 37945689, 2023). "The decrease in CCL5 levels during malaria infection has been suggested to be a result of malaria-induced thrombocytopaenia." (PMID 30442134, 2018). "Out of the six proteins, three were identified as showing increased levels (CRP, CSF1, LBP) in malaria patients compared to controls while the remaining three displayed decreased levels (CCL5, CTSD, SPARC)." (PMID 30442134, 2018). "In another study, IL-8/CXCL8 was elevated in CSF of non-fatal CM cases of P. falciparum-infected children, while MCP-1/CCL2, MIP-1α/CCL3, MIP-1β/CCL4, and RANTES/CCL5 levels were comparable to malaria-free controls." (PMID 28775960, 2017). "Increased levels of CXCL8 and CXCL9 as well as reduced levels of CCL5 (also known as RANTES) have been observed in severe malaria patients." (PMID 24476686, 2014). "Changes in levels due to inflammation, as shown with CEBPA, CRP and CCL5 protein levels, were more exacerbated in the CM than the DC samples suggesting a stronger inflammatory response in malaria-infected patients than in other diseases." (PMID 24743550, 2014). "This is further supported by the observation that CCL5 production in IFN-γ-stimulated PBMCs from malaria-infected children decreased with increasing levels of intramonocytic pfHZ." (PMID 24476686, 2014). "The group of subjects with mild malaria displayed a substantial loss of the number of significant interactions in the network and the pro-inflammatory cytokines IFN-γ, TNF and CCL5 had the highest number of connections." (PMID 23433077, 2013). "Chemokines of the C-C or β subfamily, including macrophage inflammatory proteins 1 (MIP-1α), MIP-1β, and Regulated on Activation Normal T cell Expressed and Secreted (RANTES/CCL5) modulate many infectious and inflammatory diseases, including malaria." (PMID 18489763, 2008). "The immunity related genes that are down-regulated in the malaria severity signature are: PRF1, GNLY, OAS2, MX1, OAS3 and CCL5." (PMID 29642892, 2018). "Six representative examples, showing both increased (ADSSL1, CEBPA, CRP, LBP) and decreased protein levels (CCL5, SPARC) in malaria patients compared to controls are shown in." (PMID 30442134, 2018). "Three proteins displayed lower protein levels in the malaria cases compared to the controls; anti-adhesive SPARC (also known as Osteonectin), cell migration chemoattractant CCL5 (also known as RANTES) and apoptotic CTSD." (PMID 30442134, 2018). "The set of proteins that was denoted ‘Malaria decreased’ contained fibulin-1 (FBLN1) and RANTES (CCL5), both involved in endothelial cell death, whilst glutathione peroxidase (GPX1) protects from oxidative stress." (PMID 24743550, 2014). "Chemokine release is also associated with the malaria blood stage, but HZ alone did not induce the secretion of any of the chemokines investigated, CXCL8 (IL-8), CXCL9, CXCL10, CCL2 and CCL5." (PMID 40717771, 2025). "mDCs from malaria-exposed adults also secreted the Th1-associated chemokines CXCL9 (MIG) and CXCL10 (IP-10) as well as CCL2 but no CCL5." (PMID 33407502, 2021). "Co‐incubation of macrophages with XO and iRBCL also induced synergistic production of the chemokines IL‐8, CCL5, and CCL2, which are essential in the recruitment and activation of leukocytes to sites of inflammation and are also elevated during malaria." (PMID 31265218, 2019).
malaria (continued). "Severe malaria patients exhibit high levels of serum pro-inflammatory cytokines (TNF, IL-1β, IL-6, IL-8, IL-12, IFNγ) and chemokines (CCL2, CCL5, CXCL9, CXCL10), and lower levels of regulatory cytokines (IL-10, TGFβ, PGE2) compared to those with mild and asymptomatic malaria." (PMID 27792766, 2016). "In addition to producing type I IFNs, DCs produce a wide range of pro-inflammatory cytokines, including TNF-α, IL-12, and IL-6, and chemokines, such as CXCL1, CXCL2, CCL2, CCL5, CXCL9, and CXCL10 in response to malaria parasites, and play crucial roles in malaria immunity and pathogenesis." (PMID 30619355, 2018).
Hypertension (33 papers, 2005 to 2026). The presence of chronic increased pressure in the systemic arterial system. "While our study showed that CCL5-deficient mice are protected from Ang II-promoted cardiac remodeling, this discrepancy may be attributed to differences in mouse strains and the severity of the hypertension model." (PMID 41346713, 2026). "These disparate findings suggest that CCL5 plays context-dependent roles in hypertension-induced end-organ injury, a topic that remains under active investigation." (PMID 41346713, 2026). "In contrast, genetic deletion of CCL5 exacerbated kidney damage during Ang II-dependent hypertension." (PMID 41346713, 2026). "To delineate the principal biological pathways through which CCL5 contributes to hypertension-induced cardiac remodeling, we performed a ClueGO-based functional annotation of CCL5-regulated genes." (PMID 41346713, 2026). "This work offers new perspectives on platelet biology, emphasizing how CCL5 enhances platelet activation and promotes a pro-fibrotic macrophage phenotype during hypertension-induced cardiac remodeling." (PMID 41346713, 2026). "Pharmacological platelet inhibition and platelet depletion/reconstitution experiments provide further evidence for the critical role of CCL5-mediated platelet function in promoting cardiac inflammation and remodeling during Ang II-induced hypertension." (PMID 41346713, 2026). "The heightened expression of CCL5 in response to EVs from hypertensive rats highlights a potential mechanism by which hypertension can alter immune cell migration and infiltration in the brain and other organs." (PMID 38539860, 2024). "It is known that γδT lymphocytes synthesize molecules with a confirmed role in vascular wall fibrosis and thus in the development of hypertension such as IL-17, IFNγ, TNFα, or CCL5." (PMID 39195289, 2024). "Although CCL5 expression increases in the kidney during hypertension, its effects on renal inflammation and injury seem to be protective." (PMID 34575833, 2021). "Peripheral blood T cells from the miR-214−/− mice infused with Ang II exhibited reduced chemotaxis towards key chemokines involved in hypertension—CCL5 (C-C motif chemokine ligand 5) and CXCL10 when compared with WT mice." (PMID 32065054, 2020). "Previous studies have shown that there is a significant positive correlation between CCL5 expression and blood pressure in the Ang II-induced hypertension mouse model." (PMID 32194402, 2020). "Similarly, both pharmacological inhibition and genetic deletion of CCL5 mitigated Ang II-promoted vascular dysfunction in hypertension models." (PMID 41346713, 2026). "Similarly, in the CNS, chemokines such as CCL5 and CXCL1 are implicated in neuroinflammation associated with hypertension." (PMID 40859641, 2025). "CCL5 may act as a regulatory factor against Ang II-induced hypertension, but has also been recognized as an indicator of short-term mortality in patients with CVD." (PMID 34292876, 2021). "They indicate that tissue expression of CCL2 and CCL5 is raised in hypertension." (PMID 34575833, 2021). "Increased levels of CCL5 have been documented in both the central nervous system and peripheral organs such as the kidneys in hypertensive rats, implying a systemic response that could exacerbate hypertension." (PMID 38539860, 2024). "This may be explained by the blockade of one chemokine leading to the upregulated expressions of other cytokines that exacerbate RAS-dependent hypertension, as CCL2 blockade abrogates the enhanced renal macrophage infiltration and interstitial fibrosis in CCL5-deficient mice." (PMID 32194402, 2020). "Taken together, these analyses support an enhanced gene regulatory influence of adrenal Agtr1a as well as a diminished gene regulatory influence of Th, Ccl5, Agtr1a, and Il1b from the CVLM in regulating the progression of hypertension in females." (PMID 39514592, 2024).
Hypertension (continued). "Opposing this recruitment, the mononuclear cell chemokine C-C motif chemokine 5 (CCL5) constrains CCL2 expression, macrophage infiltration, and kidney damage and fibrosis in hypertension via blood pressure-independent mechanisms." (PMID 36232403, 2022). "Furthermore, this process was related to a higher level of inflammatory chemokine expression (CCL2 and CCL5) in PVAT, whose crucial role in hypertension and other CVDs is well established [27,]." (PMID 33131726, 2020). "CCL5 expression is upregulated in the aorta and pVAT during RAS-dependent hypertension." (PMID 32194402, 2020). "Genetic deletion of CCL5 did not alter hypertension triggered by Ang II." (PMID 41346713, 2026). "Chemokines also take part in the pathogenesis of hypertension, including monocyte chemoattractant protein-1 (MCP-1, CCL2), Gro-α (growth-related oncogene), interferon-inducible protein (IP-10, CXCL10) interleukin-8 (IL-8; CXCL8), CXCL1/RaNTeS (CCL5)/CCR5 and fractalkine (FKN aka CX3CL1)/CX3CR1." (PMID 32848763, 2020). "Finally, due to CCR5’s lack of specificity for CCL5, identifying the key ligands responsible for CCR5 activation in CVDs and hypertension would be highly valuable for advancing the literature." (PMID 40859641, 2025). "While prior studies have focused on tear cytokines in diabetic retinopathy, our study identified elevated tear cytokines (IL-6, CXCL8, IL-15, CCL5, and VEGF) in diabetic patients without diagnosed retinopathy, persisting after controlling for age, hypertension, and dyslipidemia." (PMID 41030257, 2025).
multiple sclerosis (33 papers, 2005 to 2026). A progressive autoimmune disorder affecting the central nervous system resulting in demyelination. "Van Veen and colleagues found that the low-producer CCL5 allele rs2107538-G was associated with reduced risk of severe axonal loss, whereas the high-producer CCL5 allele rs2107538-A was associated with a worse clinical course of multiple sclerosis." (PMID 36983384, 2023). "In this work, we report the first amperometric immunosensor developed to date for the determination of the CCL5 chemokine, a reliable biomarker for multiple sclerosis autoimmune disease." (PMID 36005006, 2022). "Selective neutralization of CCL5 resulted in diminished leukocyte infiltration into the CNS and reduced neurological disability in a viral model of multiple sclerosis." (PMID 36235456, 2022). "Previous studies indicated that serum levels of CCL5 were significantly increased in multiple sclerosis (MS) patients and in experimental autoimmune encephalomyelitis (EAE) animals." (PMID 35983033, 2022). "The interaction of CCL5 with its receptor has been shown to have a role in neuroinflammatory diseases such as multiple sclerosis." (PMID 34869411, 2021). "In taiep rats, an animal model for multiple sclerosis, CCL5 and its receptor CCR5 is down-regulated in comparison to Sprague-Dawley rats." (PMID 29375328, 2017). "CCL5, which was also induced in our infected organoids, is an important chemokine produced by astrocytes in response to inflammation, especially in diseases such as multiple sclerosis and intracerebral hemorrhage." (PMID 40985448, 2025). "Moreover, BMP signaling has been found to regulate CCL5 expression in multiple sclerosis, influencing the recruitment of macrophages and T lymphocytes." (PMID 40843375, 2025). "In addition, it has been demonstrated that CCL5/RANTES contributes to the development of Parkinson Disease and multiple sclerosis, i.e., other neurodegenerative illnesses." (PMID 38674726, 2024). "Serum level of CCL5 chemokine is considered an emerging biomarker for multiple sclerosis (MS)." (PMID 36005006, 2022). "In chronic neurodegenerative diseases of the brain, such as Multiple sclerosis, Alzheimer's disease and HIV-dementia, CCL5 signaling is associated not only with its classical definition as a chemoattractant for monocytes, but also with the initiation of neuroprotective mechanisms in neurons." (PMID 28936366, 2017). "Although the recruitment mechanism of proinflammatory macrophages into heart was complex, some chemokines such as CCL5 was reported to play roles in disease pathogenesis and its antibody could inhibit the progression of some immune diseases like multiple sclerosis." (PMID 38185631, 2024). "Research indicates that CCL5 plays a crucial role as a downstream pathway in the BMP signaling route in demyelinating diseases of the central nervous system, such as multiple sclerosis." (PMID 40843375, 2025). "In multiple sclerosis, CC chemokines such as CCL2 and CCL5 promote central nervous system inflammation by regulating immune cell migration." (PMID 39104791, 2024). "In experimental multiple sclerosis mouse model, gal3−/− mice infected with Theiler’s murine encephalomyelitis virus have reduced CCL2, CCL5, CCL8, and CXCL10 expression and lower number of infiltrating cells in the brain subventricular zone." (PMID 28217127, 2017). "The CCL5-mediated control of glutamate release at chemical synapses could be relevant either to the onset of psychiatric symptoms that often accompany the development of multiple sclerosis (MS), but also it might indirectly give a rationale for the progression of inflammation and demyelination." (PMID 28928746, 2017).
periodontitis (33 papers, 2010 to 2025). An acute or chronic inflammatory process that affects the tissues that surround and support the teeth. "Alleles A and G of the CCL5-403 polymorphism were significantly associated with different subtypes of periodontitis." (PMID 37927745, 2023). "A study of the Taiwanese population showed that the AA and AG genotype—403 single nucleotide polymorphism of chemokine ligand 5 (CCL5-403)—is associated with a higher incidence of generalized aggressive periodontitis." (PMID 38139161, 2023). "Although CCL5 has been implicated in the pathomechanism of periodontitis, a comprehensive understanding of its molecular mechanisms and significance remains elusive, hindering the development of drugs targeting this chemokine or its receptors." (PMID 38139161, 2023). "A Taiwanese study found CCL5 single-nucleotide polymorphism to be related with aggressive periodontitis." (PMID 37510279, 2023). "For instance, CCL2 and CCL5 are elevated in gingival crevicular fluid in patients with generalized aggressive periodontitis, and CCL2 is increasingly expressed in fibroblasts from periodontitis patients." (PMID 39781111, 2025). "Lastly, it should be mentioned that another cytokine involved in periodontitis immunopathology is RANTES/CCL5." (PMID 38792574, 2024). "To date, there has been no review in the literature summarizing the importance of the chemokine CCL5 in the molecular mechanisms of periodontitis." (PMID 38139161, 2023). "Another study showed that GCF collected from probing depths <3 mm in patients with periodontitis had lower CCL5 concentrations than GCF collected from probing depths >6 mm." (PMID 38139161, 2023). "The results of studies analyzing gingival biopsies from patients with periodontitis show that CCL5 expression is higher in patients with periodontitis than in healthy subjects, confirming the results of GCF analyses." (PMID 38139161, 2023). "Only a subset of these 24 CC chemokines are important in the pathogenesis of periodontitis, and CCL5 is one of them." (PMID 38139161, 2023). "Periodontitis is not only a disease of the periodontium, but it also influences systemic health in which CCL5 plays an important role." (PMID 38139161, 2023). "It discusses the involvement of CCL5 in pathological processes during periodontitis, such as connective tissue and bone destruction." (PMID 38139161, 2023). "CCL5 is not only a marker for periodontitis, it is also involved in the pathological processes of this disease, as confirmed by the results of research on the CCL5 gene polymorphisms." (PMID 38139161, 2023). "In patients with generalized aggressive periodontitis, the total CCL5 in GCF was also higher than in healthy subjects and higher in progressive periodontitis (active sites) than in inactive sites." (PMID 38139161, 2023). "The available literature contains the results of many studies on CCL5 in the gingiva of patients with periodontitis, usually showing similar results, but with some notable discrepancies." (PMID 38139161, 2023). "Studies in patients with chronic periodontitis and aggressive periodontitis showed reduced blood levels of CCL5 compared to healthy subjects and reduced plasma levels of CCL11 and CXCL9 in patients with chronic periodontitis." (PMID 38139161, 2023). "The total CCL5 in the GCF samples at one site was found to be higher in patients with chronic periodontitis than in healthy subjects." (PMID 38139161, 2023). "After treatment of periodontitis, CCL5 concentrations in GCF decreased and returned to levels observed in healthy subjects." (PMID 38139161, 2023). "For this reason, it is reasonable to assume that the greater the synthesis of CCL5, the greater the likelihood of developing periodontitis." (PMID 38139161, 2023). "CCL5 chemokine expression in periodontitis patients is elevated in the affected gums and gingival crevicular fluid, and bacterial activity is a significant factor in increasing CCL5 expression in periodontitis patients." (PMID 38139161, 2023).